ERBB2 (erb-b2 receptor tyrosine kinase 2)
Diseases named in the same sentence as ERBB2 in open-access papers (continued):
Sharing a sentence is not in itself a finding about the gene and the disease.
breast cancer (continued). "However, in a recent study evaluating ERBB2 mutations using ctDNA in patients with advanced breast cancer, the frequency of ERBB2 mutations was 8.9% and this was higher in HER2-positive tumors than in HER2-negative tumors." (PMID 36029565, 2022). "On the other hand, ERBB family receptor tyrosine kinases are commonly overexpressed in breast cancers, in particular, ErbB2 or HER2/neu amplification constitute a major breast cancer subtype found in 15–30% of breast cancers while ErbB4 overexpression is less common." (PMID 35846378, 2022). "For example, it was demonstrated in ErbB2-positive breast cancer that laminin and integrins a6b4, a3b1 could lead to acquired resistance to lapatinib and trastuzumab through mitogenic and pro-survival signaling." (PMID 35965583, 2022). "We further tested whether understanding of the mechanisms by which ErbB2 downregulates BLNK can potentially be used for designing anoikis-promoting breast cancer treatments." (PMID 35933456, 2022). "In breast cancer, the expression of ErbB2/HER-2 is predictive of the response rate of an inhibitor." (PMID 35160172, 2022). "Using a transcriptome dataset for 51 breast cancer cell lines including luminal, ERBB2-amplified, basal and claudin-low lines, we determined whether expression of CA12 is also associated with that of ESR1 and how it compares with PGR expression." (PMID 36358871, 2022). "Among all breast cancer subtypes, the triple-negative type is more likely to recur, and shows the lowest 5-year survival rate (85% for nonmetastatic triple negative cancer, 94% for hormone-receptor-positive, and 99% for ERBB2-positive cancer)." (PMID 35209095, 2022). "Importantly, in each case they detect 17q12 which contains ERBB2, a well-known driver gene for HER2+ breast cancer." (PMID 35885119, 2022). "Overexpression of ErbB2 promotes breast cancer cells to grow rapidly." (PMID 36140365, 2022). "In addition, two ongoing clinical studies in patients with advanced stage breast cancer employ CAR T cells targeting ErbB2 (Human Epidermal growth factor Receptor 2, HER2) and mesothelin." (PMID 36359405, 2022). "Given the well-characterized role of ERBB2 in breast cancer pathogenesis, we next analyzed breast cancer datasets available within the GEO database to determine if there are any similarities in the ERBB2-mediated enrichment of pathways in breast and colon cancer patients." (PMID 36612126, 2022). "From a biomolecular perspective, the expression of three molecules, estrogen receptor alpha (ERα), progesterone receptor (PR), and epidermal growth factor 2 receptor (ERBB2, formerly known as HER2 or HER2/neu), is important in the diagnosis, classification, and targeting of breast cancer." (PMID 35625915, 2022). "Pearson’s correlation and Spearman’s correlation analyses were performed for the three groups of breast cancer patients, i.e., BRCA1-mutated, BRCA2-mutated, and ErbB2-amplified breast cancer patients, depending on the normal or non-normal distribution of expression data." (PMID 35740092, 2022). "In another clinical trial, LY3039478 treatment resulted in a partial response that lasted 9.5 months in a patient with Erbb2 (Her2)-negative breast cancer cells with a FBXW7 mutation." (PMID 35346215, 2022). "The ERBB2 gene promoter has been used in some works, as in a clinical trial for breast cancer where the patients received intratumoral injection of a plasmid that encodes the E. coli cytosine deaminase under the control of the ERBB2 gene promoter to activate the prodrug fluorocytosine." (PMID 36145609, 2022). "ErbB2 inhibits breast cancer cell anoikis by partially understood mechanisms." (PMID 35933456, 2022).
breast cancer (continued). "This interaction is also relevant from the standpoint of cancer therapy since the large size of the MUC4 complex, brought into proximity of ErbB2, results in masking of the ErbB2 epitope for trastuzumab, a monoclonal antibody used in the treatment of ErbB2-positive breast cancer." (PMID 35205690, 2022). "It has been reported that ERBB2 is likely to be amplified in breast cancer." (PMID 35416406, 2022). "In this cohort study, the delay of the initiation of AHT past 150 days in patients with HR-positive, ERBB2-negative breast cancer who did not receive chemotherapy was associated with diminished survival." (PMID 35166783, 2022). "Additionally, the rates of false positive ERBB2 amplification by NGS for breast cancer (6%) is similar to inter-laboratory differences seen with IHC/FISH testing for breast cancer." (PMID 35126865, 2022). "In addition, we found that BLNK upregulation in human ErbB2-positive breast cancer cells blocks their ability to form tumors in mice." (PMID 35933456, 2022). "ERBB2 mutations were identified in 5/41 CDK4/6-resistant tumor, and preclinical work demonstrated that ERBB2 mutation activates downstream MAPK/AKT/mTOR and confers resistance to CDK4/6 blockade in breast cancer cells." (PMID 35804935, 2022). "Importantly, treatment with NRG4 and simultaneous blockage of ERBB2, which is expected to specifically trigger the activation of ERBB4-ERBB4 homodimers, restrained the growth of HER2+ breast cancer cells more efficiently than anti-HER2 drugs alone." (PMID 35664762, 2022). "Owing to the improved efficacy, in 2020, the US Food and Drug Administration (FDA) approved margetuximab in combination with chemotherapy as the treatment of adult patients with metastatic ERBB2-positive breast cancer who have received two or more prior anti-ERBB2 regimens." (PMID 36159262, 2022). "Human epidermal growth factor receptor 2 gene amplification (HER2; ERBB2) test is well established to determine whether a breast cancer patient is eligible for anti-HER2 target therapy." (PMID 36358732, 2022). "Breast cancer is a highly heterogeneous tumor that is currently classified by three molecular markers, including estrogen receptor (ER), progesterone receptor (PR) and HER2 (also called ERBB2)." (PMID 35387130, 2022). "In addition, in breast cancer, the OS of the patients with ERBB2 amplification was significantly longer than those with ERBB2 fusions with amplification." (PMID 36276102, 2022). "Meanwhile, ERBB2 fusion has been found in colorectal cancer and breast cancer, which may be related to response to HER2-targeted drugs." (PMID 36276102, 2022). "The study reported that SRC modulates the antibody Trastuzumab that targets the human epithermal growth factor receptor-2 (HER-2 or ERBB2) response in breast cancer, and that activating SRC by phosphorylation at Tyr416 was required for regulating the multiple resistance pathways." (PMID 35954330, 2022). "An in vitro cellular uptake study was also conducted for tamoxifen citrate loaded nanolipid vesicles conjugated with antibody (FITC anti-human CD 340 (erbB2/HER-2)) in MDA-MB-453 (ER-negative) breast cancer cells for different concentration, such as 50 and 100 μg/mL for 1 and 2 h." (PMID 35745897, 2022). "As such, this family of receptors is often the target of genetic alterations in cancers that result in their constitutive activation: e.g. EGFR is frequently mutated in lung cancers and amplified in gliomas, while ERBB2 (Her2) is frequently amplified in breast cancers." (PMID 36480552, 2022). "Moreover, we established that BLNK promotes anoikis by activating p38 MAP kinase and that ErbB2-dependent BLNK downregulation blocks breast cancer cell anoikis." (PMID 35933456, 2022). "To test this hypothesis, we first employed BT474 cells, a human breast cancer ERBB2-overexpressing cell line, which expresses ERBB4 at intermediate/high levels." (PMID 35664762, 2022).
breast cancer (continued). "Similarly, lovastatin potentiated the effects of lapatinib, an ErbB2 TKI, to strongly suppress in vitro and in vivo growth of ErbB2 positive breast cancer xenografts." (PMID 35205690, 2022). "Mutations in BRCA1 and BRCA2, in addition to ERBB2, were also newly present in brain metastatic tumors and not detected in primary breast tumors in eight out of 22 breast cancer patients." (PMID 36507516, 2022). "However, at the same time, active AKT1 is necessary for mammary tumor development driven by ErbB2 or PyMT, since its ablation in double transgenic mice interferes with tumor growth." (PMID 35681625, 2022). "ERBB2 is up-regulated in multiple tumors located in breast, bladder, pancreas, ovary, and esophagus, especially in tumors with poor prognostic characteristics; in breast cancer, high expression of ERBB2 has become one of the hallmarks of poor prognosis." (PMID 36437939, 2022). "As expected, we could show that the synthesized and fluorescence-labeled anti-ErbB2-anti-ErbB3-bsFabs exhibited improved fluorescence intensities in mammalian breast cancer cell lines compared with the single Fabs alone." (PMID 35328563, 2022). "This is supported by the study that the development of lapatinib resistance of ERBB2-positive breast cancer cells is correlated with upregulation of autophagy where the addition of autophagy inhibitors reversed lapatinib resistance by inhibiting cell proliferation and increasing cell death." (PMID 33801244, 2021). "Meanwhile, LSM4 was also correlated with “Immune response IL-15 signaling via MAPK and PI3K cascade”, “Cell cycle spindle assembly and chromosome separation”, and “Mitogenic action of ErbB2 in breast cancer”, which are immune- and cell cycle-related pathways that play roles in BRCA growth." (PMID 34638387, 2021). "Knockdown of Akt1 and Akt3 in ErbB2-positive Erα-negative mouse mammary tumor C4 cells caused a substantial decrease in cell proliferation whereas Akt2 knockdown had only a modest effect." (PMID 34298660, 2021). "Recently, PET-based detection and monitoring of metastasis cancer has utilized the following antibodies: 111In-labeled anti-CDH17 (gastric cancer), 177Lu-labeled anti-CD55 (lung cancer), and radio-labeled anti-ERBB2 (various labeling, including 89Zr, 64Cu, 111In) (breast cancer)." (PMID 34680307, 2021). "ErbB2, a classical receptor tyrosine kinase, is frequently overexpressed in breast cancer cells." (PMID 33854045, 2021). "ERBB2-positive breast cancer is treated with directed therapy as the standard of care." (PMID 34680187, 2021). "However, the overexpression of this receptor allows the development of ErbB2-targeting therapeutic agents, such as trastuzumab, which was used for the past two decades in breast cancer therapy." (PMID 33669783, 2021). "LF15 also harbored a pathogenic mutation in ERBB2 (p.V842I), not described in lungs, but detected in gastric cancers, breast cancers, and colorectal adenocarcinomas." (PMID 34198671, 2021). "For the murine HER2-positive breast cancer cell line, the brain metastatic cells expressing avian erythroblastosis oncogene B2 (ErbB2) (ErbB2-BrM2) were established from MMTV-driven NeuNT transgenic murine mammary tumor cells by repetitive in vivo selection using the intracardiac injection method." (PMID 33672831, 2021). "One mechanism for the current clinical treatment of ERBB2-positive breast cancer with the ERBB2 antibody Herceptin/Trastuzumab (and possibly others) may be due to autophagy inhibition by the antibody-induced ERBB2 degradation and ATG12 downregulation." (PMID 33801244, 2021). "Finally, we investigated if the distribution of PAM50 subtypes within HER2-low breast cancer differed according to ERBB2 mRNA levels." (PMID 33397968, 2021). "It will be of considerable value to assess whether low CHIP expression may serve as a correlative marker for Bortezomib plus Trastuzumab responsiveness in ErbB2-overexpressing breast cancer." (PMID 34439093, 2021).
breast cancer (continued). "More, the druggable ERBB2 amplification occurred in a quarter of young adult breast cancer cases." (PMID 34788626, 2021). "To assess the associations between cellular heterogeneity for ERBB2 copy number and mutant PIK3CAH1047R as well as response to treatment and changes in heterogeneity due to therapy, we performed STAR-FISH on cases from 2 uniformly treated cohorts of patients with HER2+ breast cancer." (PMID 33886505, 2021). "Moreover, ERBB2-overexpressing breast cancer cells gained resistance to HER2 blockade via increasing the FGF3/4/19 copy number and FGFR phosphorylation." (PMID 34638374, 2021). "These new insights suggest that reduced CHIP expression may specify ErbB2-overexpressing breast cancers suitable for combined treatment with Trastuzumab and ER stress inducing agents." (PMID 34439093, 2021). "To examine whether ERBB2 promotion of autophagy leads to treatment resistance of breast cancer cells, we treated the breast cancer cell lines with the chemotherapeutic drug Taxol (paclitaxel)." (PMID 33801244, 2021). "Moreover, CD151 has been shown to activate RhoA by facilitating integrin α3β1 and Rho controls dimerization of ErbB2, thus promoting motility and metastasis of breast cancer." (PMID 34108040, 2021). "Besides, we have previously demonstrated that PTPRO inhibited ERBB2-driven breast cancer through dephosphorylation leading to dual effects of ERBB2 signaling suppression and endosomal internalization of ERBB2." (PMID 34650968, 2021). "ErbB2 is overexpressed in 20-30% of breast cancers and is correlated with poor prognosis." (PMID 33995662, 2021). "IHC analysis confirmed ERBB2 overexpression in ++Oxtr mammary tumors." (PMID 34099636, 2021). "About 78.2% of the BRCA1-deficient mammary tumors do not express ERα or PR, though about 60% of the tumors showed detectable level of ERBB2." (PMID 34815798, 2021). "Combined with the discovery that circ-ERBB2 was localized in the cytoplasm, we continued to investigate whether circ-ERBB2 exerted a regulatory function in HER2-positive breast cancer through the competing endogenous RNA (ceRNA) mechanism." (PMID 34732216, 2021). "However, studies have shown that ERBB2 suppression is a common anticancer strategy, with 25% of breast cancer patients with ERBB2 over expression." (PMID 34285700, 2021). "As expected, subtype distribution differed in HER2-low breast cancer according to ERBB2 levels (p < 0.001) with the T2-3 group being more enriched with Luminal A, Luminal B and HER2-E subtypes (51.5%, 34.9%, and 6.3%) compared to the T1 group (31.7%, 15.8%, and 3.6%)." (PMID 33397968, 2021). "Overexpressed ErbB2/HER2 receptor drives up to a quarter of breast cancers." (PMID 34439093, 2021). "Since CHIP is known to serve as a key regulator of protein quality control, it is reasonable to posit that lower levels of CHIP in ErbB2-overexpressing breast cancer cells could promote the accumulation of unfolded proteins and elevate ER stress." (PMID 34439093, 2021). "For example, patients with breast cancer are often classified into three subtypes according to the molecular characteristics, namely the expression of estrogen or progesterone receptors and human epidermal growth factor 2 (ERBB2, also named HER2)." (PMID 33898311, 2021). "Moreover, fatty acid synthase (FAS) and ErbB2 have been shown to promote breast cancer cell migration." (PMID 34944904, 2021). "Notably, cancer patients with high p140Cap expression in their primary tumors have a lower probability of developing a distant event and ERBB2-positive breast cancer sufferers show better survival." (PMID 33079227, 2021). "These functions included the ability to sensitize in vivo against both MHC class I and MHC class II-restricted peptides and the ability to generate therapeutically-meaningful immune responses in a mouse model of HER2pos breast cancer using a known rat ErbB2/HER2 CTL epitope peptide." (PMID 34579275, 2021).
breast cancer (continued). "In one study, a single-chain antibody against the Her2/neu receptor (ErbB2) was cloned in the viral genome to confer tropism toward tumoral cells, but the engineered VSV showed poor replication in ErbB2-expressing mammary cancer cells, and directed evolution was used to improve this trait." (PMID 34040797, 2021). "The precise mechanisms by which increased PTP1B promotes tumorigenesis in ErbB2-driven breast cancers remain unknown, but this may be reliant on the promotion of RAS–MAPK signalling." (PMID 34884538, 2021). "We used phenotypic high throughput microscopy screening to identify efficient inhibitors of ErbB2-induced invasion using 1st line HER2 inhibitor trastuzumab- and pertuzumab-resistant, p95-ErbB2 expressing breast cancer cells in conjunction with the Prestwick Chemical Library®." (PMID 33939112, 2021). "Four genes (AKT1, ERBB2, KMT2C, and USP34) were associated with survival of breast cancer." (PMID 34408553, 2021). "Recall that the definition of ERBB2+ breast cancer is an overexpression of ERBB2 receptor." (PMID 33670942, 2021). "However, this overall mainly nuclear ErbB2 expression pattern was considerably different from the solely membranous expression that is known from breast cancer cells." (PMID 32591879, 2021). "Our results suggest that DMHCA may be a promising therapeutic adjunct for improving the outcome of HER2/ErbB2 breast cancer." (PMID 33780491, 2021). "HER2/ErbB2 positive breast cancer represents about 20 % of invasive breast cancers." (PMID 33939112, 2021). "We hypothesized that chromatin remodeling during EMT of HER2-high breast cancer cells could result in downregulation of ERBB2 gene expression leading to the development of drug resistance." (PMID 34575017, 2021). "ECD cleavage of ERBB2 has a close relation to breast cancer." (PMID 33947097, 2021). "Therefore, accurate detection of ERBB2 gene amplification is crucial to ensure the effective treatment of breast cancer patients." (PMID 33893247, 2021). "Our results suggest that ERBB2 gene silencing by epigenetic regulation during EMT may be a mechanism of de novo resistance of HER2-positive breast cancer cells to trastuzumab and lapatinib." (PMID 34575017, 2021). "ErbB2-upregulated breast cancers in all breast cancer cases are approximately 30%21,22." (PMID 33795719, 2021). "One such example is the amplification of ERBB2 in breast cancer." (PMID 33919156, 2021). "In addition, SORL1 expression was higher in tumors exhibiting high ERBB3 and ERBB2 expression (breast cancer patient data from the METABRIC study on the cBioportal database)." (PMID 33420373, 2021). "Breast cancer is by far the most common cancer in women with two main established molecular biomarkers for systemic therapy, estrogen receptor (ER) alpha and epidermal growth receptor 2 (ERBB2/HER2)." (PMID 34527184, 2021). "The ErbB2 positive breast cancer subtype represents around 20% of human breast cancer." (PMID 34708040, 2021). "ERBB2 gene amplification is observed in 20–30% of patients with breast cancer." (PMID 34685621, 2021). "Herein, endogenous Pparγ1 promoted ErbB2-mediated mammary tumor onset and progression." (PMID 33946495, 2021). "In breast cancer, a positive correlation between expression of ErbB2 and MSI1 was observed." (PMID 33541259, 2021). "Thus, ErbB2 appears to play a significant role in suppressing DEPTOR transcription in ErbB2 positive breast cancer cells." (PMID 33854045, 2021). "Hence, developing ERBB2-targeting strategies to improve the therapy of ERBB2-overexpressing breast cancer remains a high priority." (PMID 34259866, 2021). "Thus, in this model of HER2 breast cancer, cell-of-origin, reproductive history, NeuNT/Erbb2 locus amplification and the activation of specific branches of the WNT signalling pathway all interact to drive inter-tumour heterogeneity." (PMID 34003256, 2021). "Circ-ERBB2 was elevated in the tumor tissues of HER2-positive breast cancer patients." (PMID 34732216, 2021).